PRODH (proline dehydrogenase 1)
Diseases named in the same sentence as PRODH in open-access papers (continued):
Sharing a sentence is not in itself a finding about the gene and the disease.
schizophrenia (36 papers, 2007 to 2025). A major psychotic disorder characterized by abnormalities in the perception or expression of reality. "PRODH was also associated with psychiatric disorders such as schizophrenia when there is a heterozygous mutation." (PMID 40642607, 2025). "A human-specific HERV insertion (hsERV_PRODH) serves as an enhancer for the schizophrenia-linked gene PRODH, upregulating its expression via low methylation and SOX2 binding, underscoring the role of HERV in epigenetic and transcriptional regulation." (PMID 41200560, 2025). "More recently, more than 8 single nucleotide polymorphisms (SNP) of PRODH have been linked to schizophrenia." (PMID 37815900, 2024). "PRODH, which catalyzes the first step of proline degradation, has been reported as a susceptibility gene for schizophrenia." (PMID 37815900, 2024). "Two hundred and thirty metabolic genes were identified to be schizophrenia-associated, of which only 10 were found to be common in both databases, including PRODH." (PMID 37815900, 2024). "In our study, we first mapped the expression of the schizophrenia risk gene encoding PRODH and identified its specific enrichment in the oriens layer of the dorsal hippocampus." (PMID 37815900, 2024). "Refseq genes in this region include FAM230F, DGCR6, PRODH, DGCR5, with pathogenic PRODH variants associated with autosomal recessive hyperprolinemia type I or autosomal susceptibility to schizophrenia." (PMID 34938854, 2021). "Our study supports the findings from the literature regarding the association of the PAK2, ARHGAP11B, and PRODH genes with schizophrenia and/or bipolar disorder." (PMID 33510659, 2020). "Our findings support the association of the PAK2, ARHGAP11B, and PRODH genes with schizophrenia and/or bipolar disorder." (PMID 33510659, 2020). "Editors' choice: A Drosophila model to study the role of PRODH, a schizophrenia-associated gene, in behavioral disorders." (PMID 28331058, 2017). "A nearly full-length ERV-K insertion near the PRODH gene, known to be associated with schizophrenia and other neuropsychiatric disorders, has been shown to work in concert with the internal PRODH CpG island to activate the gene." (PMID 28439515, 2017). "PRODH maps to chromosome 22q11.2, a region associated with the highest known genetic risk for schizophrenia, aside from that shared by monozygotic twins." (PMID 27622935, 2016). "This region spanned the DiGeorge syndrome critical region gene 5 and 6 (DGCR5 and DGCR6) as well as the proline dehydrogenase 1 (PRODH) gene implicated in schizophrenia and hyperprolinemia type 1." (PMID 26933844, 2016). "The proline dehydrogenase (PRODH) gene, which encodes the enzyme that catalyzes proline catabolism, maps to human chromosome 22q11.2, a region conferring risk of schizophrenia." (PMID 27622935, 2016). "Despite these mixed findings, the data still support a functional role for PRODH variants and hyperprolinemia in the pathophysiology of schizophrenia." (PMID 24498354, 2014). "In the present study, we aimed to associate 12 PRODH polymorphisms, and especially functional variants, with schizophrenia and other clinical variables such as treatment resistance, age of onset, and positive and negative symptoms." (PMID 24498354, 2014). "This study represents the first report of the effects of PRODH polymorphisms on brain morphology in both patients and healthy controls, testing for the interaction between this SNP and a diagnosis of schizophrenia." (PMID 24498354, 2014). "The other study investigated two other PRODH single nucleotide polymorphisms (SNPs - rs2008720 and rs372055) with respect to brain anatomy in a sample of 51 patients with schizophrenia." (PMID 24498354, 2014). "In this study, one PRODH variant (rs2904552 or R431H) and its haplotypes were associated with schizophrenia, with the GG genotype present at a higher frequency among patients than among healthy controls." (PMID 24498354, 2014).
schizophrenia (continued). "There is evidence from genetics that polymorphisms in the PRODH gene, encoding proline oxidase, which is located at 22q11, are associated with schizophrenia risk and that the related hyperprolinemia negatively associates with cognitive performance." (PMID 21429189, 2011). "In particular, functional variants in the PRODH gene that result in reduction of proline oxidase activity and hyperprolinemia are associated with increased risk of schizophrenia and changes in fronto-striatal structure and function." (PMID 21429189, 2011). "Based on mouse models, PRODH-deficiency showed physiological problems of cortical dopamine turnover and transmission that is similar to schizophrenia in humans." (PMID 19445674, 2009). "In conclusion, our data provide evidence that PRODH genetic variations that modulate the enzymatic activity of the POX enzyme contribute to the risk of schizophrenia through an impact on fronto-striatal processing." (PMID 18989458, 2008). "Using a translational approach, we show that functional polymorphisms in PRODH, encoding POX, are linked to risk for schizophrenia and associated with alterations in prefrontal-striatal brain circuits involved in working memory and cognitive gating." (PMID 18989458, 2008). "We show that the schizophrenia susceptibility gene, PRODH, conveys its risk through a variation that increases its enzyme activity." (PMID 18989458, 2008). "Here, we show in a family-based sample that functional polymorphisms in PRODH are associated with schizophrenia, with protective and risk alleles having opposite effects on POX activity." (PMID 18989458, 2008). "In the same direction association studies have reported several genes of this region associated with risk to develop schizophrenia and bipolar disorder, including PRODH, COMT, ZNF74, PCQAP, UFD1L, ZDHHC8, DGCR2 and SNAP29." (PMID 18284679, 2008). "Heterozygous pathogenic variants in PRODH have been associated with an increased risk of schizophrenia, and proximal deletions excluding TBX1 but showing syndromic features (particularly neurological ones) have suggested candidate genes such as DGCR6 (OMIM *601279) and PRODH." (PMID 41165438, 2025). "Our study demonstrates that schizophrenia-like behaviors may arise from dysregulated proline metabolism due to the loss of PRODH and are associated with altered neuronal morphology and function in mice." (PMID 37815900, 2024). "Therefore, the interaction between COMT and PRODH genes can cause an augmentation in dopamine activity, predisposing the patient to psychosis and schizophrenia." (PMID 38392589, 2024). "In addition, mutations in PRODH (Proline Dehydrogenase 1), located on 22q11.21, have been linked with susceptibility to schizophrenia (SCZD4)." (PMID 37486921, 2023). "Despite the association between variants in PRODH and an increased risk of schizophrenia shown in some studies, the potential role of this gene in psychiatric diseases remains unclear." (PMID 36980952, 2023). "Mutations in the PRODH gene coding proline dehydrogenase are thought to be linked to behavioral alterations in schizophrenia, but the role of PRODH in their etiology remains unclear." (PMID 33510659, 2020). "Mutations in the proline dehydrogenase gene PRODH are linked to behavioral alterations in schizophrenia and as part of DiGeorge and velo-cardio-facial syndromes, but the role of PRODH in their etiology remains unclear." (PMID 28331058, 2017). "Finally, PRODH-deficient mice have been shown to have a sensorimotor-gating defect, a defect considered an important endophenotype of schizophrenia." (PMID 28331058, 2017). "Associations of mutations in the PRODH gene and schizophrenia were subsequently demonstrated." (PMID 28331058, 2017). "The human-specific enhancer activity of a HERV-K (HML-2) provirus on schizophrenia-associated gene PRODH may be another active mechanism of HERV involvement in schizophrenia." (PMID 28642863, 2017).
schizophrenia (continued). "In summary, we report a functional PRODH variant associated with schizophrenia that may have a neurochemical impact, altering brain function, but is not responsible for the cortical reductions found in the disorder." (PMID 24498354, 2014). "Therefore, our study investigates the effects of 12 polymorphisms of PRODH on schizophrenia and its phenotypes." (PMID 24498354, 2014). "In summary, this study indicates that the PRODH rs2904552 polymorphism may be a genetic risk factor for developing schizophrenia, and further studies should address how disturbance of the proline pathway could affect brain function." (PMID 24498354, 2014). "Interestingly, schizophrenia is linked to the same copy number variants spanning the 22q11 region including PRODH as autism and other childhood developmental disorders, whereas bipolar disorder is not." (PMID 21429189, 2011). "First, we identified variants in PRODH related to risk for schizophrenia in a family-based sample." (PMID 18989458, 2008). "We found that the functional variants in PRODH were associated with risk for schizophrenia." (PMID 18989458, 2008). "HERVs contribute to schizophrenia pathogenesis through neuroinflammatory pathways, neurotoxicity, and the dysregulation of risk genes (e.g., BDNF, DISC1, PRODH) via epigenetic and transcriptional mechanisms." (PMID 41200560, 2025). "All of the observed behavioral defects reported herein are similar to those observed in the schizophrenia mouse model established using glutamatergic manipulation, further indicating the PRODH KD mouse exhibits schizophrenia-like behavior." (PMID 37815900, 2024). "The expression levels of two degradation enzymes, ALDH4A1 and PRODH, were lower in the brains of schizophrenia patients when compared to healthy controls." (PMID 37815900, 2024). "The expression levels of both excitatory and inhibitory neuron biomarkers were decreased when PRODH was knocked down, which is consistent with observations in schizophrenia patients." (PMID 37815900, 2024). "Among the top 40 genes associated with developmental delay, DGCR6, PRODH, DGCR5, and ZDHHC8 are potential candidates for involvement in DiGeorge syndrome pathology and schizophrenia." (PMID 37486921, 2023). "Studies of mouse models and 22q11DS patients have provided evidence supporting the idea of an epistatic interaction between COMT and PRODH as they both functionally converge on the dopaminergic system and give rise to a hyper-dopaminergic state that may predispose to psychosis and schizophrenia." (PMID 35457231, 2022). "First, to the best of our knowledge, mutations with large risk to schizophrenia have been reported in at least five genes, DISC1, NRXN1, PRODH, SHANK3, and SLC1A1 according to records in OMIM." (PMID 30745909, 2018). "A meta-analysis found that putative schizophrenia risk variants in genes including ZNF804A, PRODH, DISC1 and PPP1R1B, reduced functional connectivity, while the genetic changes examined had no overall effect on structural connectivity." (PMID 27450778, 2016). "PRODH has been frequently found deleted in schizophrenia patients, suggesting it plays a significant role in the pathophysiology of schizophrenia." (PMID 19445674, 2009). "PRODH, encoding proline oxidase (POX), has been associated with schizophrenia through linkage, association, and the 22q11 deletion syndrome (Velo-Cardio-Facial syndrome)." (PMID 18989458, 2008). "These patients did not have mutations in PRODH, indicating that proline accumulation can independently lead to schizophrenia without the presence of genetic defects." (PMID 37815900, 2024). "It has consistently been shown that PRODH knockout mice exhibit schizophrenia-like behaviors." (PMID 37815900, 2024). "Finally, some patients with schizophrenia display elevated levels of proline and the proline dehydrogenase (PRODH) gene over-expression, hence implicating abnormal proline metabolism in schizophrenia." (PMID 37298431, 2023).
schizophrenia (continued). "Interestingly, PRODH and ZDHHC8 both have single nucleotide polymorphisms (SNPs) that are closely associated with 22q11DS-related schizophrenia-like symptoms." (PMID 35457231, 2022). "PRODH catalyzes a step in the conversion of proline to glutamate, while GNB1L encodes a G-protein beta-subunit-like polypeptide; both genes have also been associated with schizophrenia and other mental disorders." (PMID 32339168, 2020). "There is an extensive literature indicating that proline dehydrogenase (PRODH) activity may be up-regulated in schizophrenia." (PMID 27076878, 2016). "PRODH is deleted in schizophrenia patients and may play a significant role in the pathophysiology of schizophrenia." (PMID 19445674, 2009). "Several recent studies have found genetic associations of schizophrenia with tag and functional single nucleotide polymorphisms (SNPs) in PRODH, although this association has not been observed in all samples." (PMID 18989458, 2008). "Taken together, proline accumulation, whether or not it is the result of PRODH deficiency, may induce schizophrenia-like behaviors." (PMID 37815900, 2024). "Focusing on neurotransmitter regulation within the prefrontal cortex’s dopaminergic circuits, this study emphasizes the role of genes like COMT, PRODH, and DRD in shaping executive functions and influencing conditions such as ADHD and schizophrenia." (PMID 38392589, 2024). "In various cancer types, schizophrenia-related genes (HTR2A, COMT, and PRODH) have different expression patterns, and the direction of down-regulation varies." (PMID 37564635, 2023). "According to the results of our investigation, the prognostic level is closely correlated with the variations in the expression of the schizophrenia-related genes HTR2A, COMT, and PRODH in various malignancies." (PMID 37564635, 2023). "In addition, this participant also had a very small 22q11.21 duplication including the PRODH and RTN4R genes both reportedly play a role in schizophrenia." (PMID 25400949, 2014). "For schizophrenia, DGCR6 and PRODH are well-known candidate genes, and DGCR5 is a long non-coding RNA gene with a high score for causing schizophrenia." (PMID 37486921, 2023).
hyperprolinemia (14 papers, 2010 to 2026). Hyperprolinemia is when there isan excess of a particular protein building block (amino acid), called proline, in the blood. "Mutations or small deletions in PRODH cause recessive hyperprolinemia (OMIM 239500) with neurologic manifestations, including seizures." (PMID 36980952, 2023). "Several reports suggested that a homozygous mutation in the PRODH gene could cause hyperprolinemia, Type I disease, which usually showed with neurologic manifestations, including ASD and seizures." (PMID 40642607, 2025). "When aggregating variant frequencies by gene, we find the highest frequency of pathogenic variants in PRODH (7.4%), associated with hyperprolinemia (OMIM 239500), followed by BTD (3.5%) and HFE (3.4%), which are linked to biotinidase deficiency (OMIM 253260) and type I hemochromatosis, respectively." (PMID 34078906, 2021). "Proline dehydrogenase (PRODH) deficiency causes an inability to oxidize proline in kidney and other tissues leading to hyperprolinemia that includes increased urinary excretion of proline as a symptom, which is also consistent with the predicted decrease in renal proline reabsorption." (PMID 20957118, 2010). "To date, studies of PRODH’s role in brain function and behavior have mainly focused on the role of hyperprolinemia in post-natal, post-mitotic neurons." (PMID 37794116, 2023). "This is consistent with findings in two earlier studies in children and adults (50 and 37 % hyperprolinemia) and is likely to be the result of hemizygosity of the PRODH gene in 22q11DS." (PMID 26055684, 2015).
colorectal cancer (9 papers, 2008 to 2024). A primary or metastatic malignant neoplasm that affects the colon or rectum. "Studies conducted in cell culture as well as animal models of colorectal cancer have shown that the inhibition of the COX-2/PGE2 pathway plays an important role in apoptosis induced by the PRODH/POX pathway." (PMID 31935820, 2020). "A similar phenomenon was reported in colorectal cancer cells, where researchers added DOX to DLD-POX cells to enhance PRODH activity, and the expression levels of all Complex I-IV were reduced." (PMID 38480845, 2024).
melanoma (9 papers, 2015 to 2025). A malignant, usually aggressive tumor composed of atypical, neoplastic melanocytes. "It suggests that PRODH/POX represents an underlying mechanism for the initiation of apoptosis in MET-treated melanoma cells." (PMID 35216470, 2022). "Interesting results concerning POX/PRODH have come from an experiment on C32 melanoma cell cultures, where metformin stimulation led to decreased cell viability via an increase in POX/PRODH." (PMID 38275897, 2024). "The role of proline dehydrogenase/proline oxidase (PRODH/POX) in the mechanism of antineoplastic activity of metformin (MET) was studied in C32 melanoma cells." (PMID 35216470, 2022). "The studies were performed on melanoma C32 cells, expressing PRODH/POX and PRODH/POX knock-out C32 cells (C32POX−)." (PMID 35216470, 2022). "MET in a dose-dependent manner strongly stimulated AMPK and PRODH/POX expressions in melanoma C32 cells." (PMID 35216470, 2022). "Several lines of evidence presented in this paper suggest that the mechanism of the anticancer activity of MET involves PRODH/POX-dependent ROS generation in melanoma cells." (PMID 35216470, 2022). "MET was found to (i) induce AMPK-stimulating PRODH/POX and (ii) inhibit collagen biosynthesis, facilitating proline availability for PRODH/POX-dependent ROS generation that induces apoptosis in melanoma cells." (PMID 35216470, 2022). "Our analysis suggested that PRODH was regulated by the neighboring LTR5_Hs enhancer during the reversion of the invasive melanoma phenotype." (PMID 33202765, 2020). "However, the stimulation of PRODH/POX by MET in melanoma cells induced ROS-dependent apoptosis, while PRODH/POX knockout abolished the effect." (PMID 35733940, 2022). "Interestingly, in present studies, we found that metformin induced PRODH/POX-dependent apoptosis in melanoma cells, which is characterized by an intense biosynthesis of collagen." (PMID 35216470, 2022). "However, stimulation of PRODH/POX by metformin in melanoma cells induced ROS-dependent apoptosis, while PRODH/POX knockout abolished the effect." (PMID 35409177, 2022). "The hypothesis was provided that metformin (MET) evokes pro-apoptotic potential by inducing PRODH/POX-dependent apoptosis in melanoma cells." (PMID 35216470, 2022). "We found that DTIC significantly affected the expression levels of various metabolic enzymes, including ADSL, PYCR1, PRODH, and FTH1, in melanoma cells." (PMID 37976135, 2023). "Since MET upregulates PRODH/POX, as was shown in this report, the process is agitated in MET-treated melanoma cells." (PMID 35216470, 2022). "In C32 melanoma cells, metformin decreases cell viability and DNA biosynthesis, while upregulating AMP‐activated protein kinase (AMPK) and proline dehydrogenase/proline oxidase (PRODH/POX) expression." (PMID 41085102, 2025). "In melanoma cells, characterized by the intense biosynthesis of collagen (proline consuming process) PRODH/POX knockout did not induce apoptosis." (PMID 35733940, 2022). "Collectively, our results indicate that the mechanism for MET-induced apoptosis in melanoma cells involves the upregulation of AMPK and PRODH/POX-dependent ROS formation and inhibition of collagen biosynthesis, increasing proline availability for PRODH/POX." (PMID 35216470, 2022). "In melanoma cells, characterized by intense biosynthesis of collagen (a proline-consuming process) PRODH/POX knockout did not induce apoptosis." (PMID 35409177, 2022).